WDR11 (WD repeat domain 11)
Description:
Involved in the Hedgehog (Hh) signaling pathway, is essential for normal ciliogenesis. Regulates the proteolytic processing of GLI3 and cooperates with the transcription factor EMX1 in the induction of downstream Hh pathway gene expression and gonadotropin-releasing hormone production. WDR11 complex facilitates the tethering of Adaptor protein-1 complex (AP-1)- derived vesicles. WDR11 complex acts together with TBC1D23 to facilitate the golgin-mediated capture of vesicles generated using AP-1.
Synonyms: BRWD2; KIAA1351; WDR15; FLJ10506; HH14; DR11; SRI1
Tractability: Antibody: its Gene Ontology location is reachable by antibodies, with high confidence. PROTAC: ubiquitination databases record sites on it; its protein half-life has been measured.
Gene: Protein-coding gene on chromosome 10 (120,851,305 to 120,909,524, forward strand). Ensembl gene ENSG00000120008.
Subcellular location: Cytoplasm, cytoskeleton, cilium basal body; Cytoplasm; Nucleus; Cytoplasm, cytoskeleton, cilium axoneme; Cytoplasmic vesicle; Golgi apparatus, trans-Golgi network
Subcellular location (Human Protein Atlas): End piece; Microtubules; Primary cilium; Cytosol; Flagellar centriole; Plasma membrane; Principal piece; Vesicles
Pathways (Reactome):
Signal Transduction: RHOH GTPase cycle
Gene Ontology:
Molecular function: protein binding
Biological process: intracellular protein transport; cilium assembly; head development; heart development; multicellular organism growth; regulation of smoothened signaling pathway
Cellular component: ciliary basal body; cilium; cytoplasm; cytoplasmic vesicle; cytosol; lysosomal membrane; membrane; nucleus; trans-Golgi network; axoneme; Golgi apparatus
Genetic constraint (gnomAD): Loss-of-function variants: 68 observed, 134.91 expected, observed/expected ratio (o/e) 0.5, 90% interval 0.41 to 0.62. The upper end of that interval is the gene's LOEUF score, 0.62, which puts it in group 2 of 6, group 1 being the genes least tolerant of losing a copy. Missense variants: 1,191 observed, 1,431.9 expected, observed/expected ratio (o/e) 0.83, 90% interval 0.79 to 0.87. Synonymous variants: 449 observed, 525.34 expected, observed/expected ratio (o/e) 0.85, 90% interval 0.79 to 0.92.
Homologues: Orthologues: chimpanzee WDR11 (100% identical), macaque WDR11 (99% identical), dog WDR11 (96% identical), guinea pig WDR11 (96% identical), pig WDR11 (96% identical), mouse Wdr11 (94% identical), rat Wdr11 (94% identical), rabbit WDR11 (84% identical), tropical clawed frog wdr11 (79% identical), zebrafish wdr11 (76% identical), Caenorhabditis elegans Y110A7A.9 (24% identical).
Diseases named in the same sentence as WDR11 in open-access papers:
WDR11 is named in the same sentence as 46 diseases in open-access papers, as found by Europe PMC text mining. Sharing a sentence is not in itself a finding about the gene and the disease. The quoted sentences say what the papers report.
Kallmann syndrome (16 papers, 2013 to 2023). Kallmann syndrome (KS) is a developmental genetic disorder characterized by the association of congenital hypogonadotropic hypogonadism (CHH) due to gonadotropin-releasing hormone (GnRH) deficiency, and anosmia or hyposmia (with hypoplasia or aplasia of the olfactory bulbs). "WDR11, a gene associated with Kallmann syndrome, is important in reproductive system development but molecular understanding of its action remains incomplete." (PMID 37516749, 2023). "The data at least argue for highly variable clinical penetrance and/or expressivity of heterozygous WDR11 variants associated with CHH/Kallmann syndrome." (PMID 34413497, 2021). "In this region, the WDR11 gene has been associated with congenital hypogonadotropic hypogonadism and Kallmann syndrome, which are human developmental genetic disorders defined by delayed puberty and infertility." (PMID 34408768, 2021). "We also ruled out oligogenism by sequencing the main genes associated with nCHH and Kallmann Syndrome, although WDR11, CHD7 and SEMA3A, other genes known to be associated with CHH, have not been analyzed." (PMID 23936060, 2013). "Thus, some Kallmann syndrome patients show mutations in WDR11 (WD repeat domain 11) that modulate HH signaling activity by regulating GLI3 processing." (PMID 37476499, 2023). "Here, we describe the first case of a 21-year-old male patient presenting with delayed puberty due to Kallmann syndrome, carrying a variant in WDR11 ostensibly leading to a truncated protein that resulted, contrary to expectations, in a mild form of ciliopathy." (PMID 35722485, 2022). "This is the first report of a variant in the WDR11 N-terminal region predicted to lead to complete expression loss that, contrary to expectations, led to a mild form of ciliopathy resulting in isolated Kallmann syndrome." (PMID 35722485, 2022). "Mutations in WDR11 can cause congenital hypogonadotropic hypogonadism (CHH) and Kallmann syndrome (KS) in humans, with unilateral or bilateral renal agenesis being a common phenotype in these patients." (PMID 36693108, 2023). "Genetic studies have revealed that WDR11 contributed to the occurrence of congenital hypogonadotropic hypogonadism and Kallmann syndrome." (PMID 34256807, 2021). "WDR11 has been implicated in congenital hypogonadotropic hypogonadism (CHH) and Kallmann syndrome (KS), human developmental genetic disorders defined by delayed puberty and infertility." (PMID 29263200, 2018). "WDR11 has been shown to interact with the transcription factor EMX1 leading to impaired development of olfactory neurons within individuals with Kallmann syndrome." (PMID 25140149, 2014). "In humans, heterozygous missense variants in the WDR11 gene have been associated with hypogonadotropic hypogonadism type 14 with or without anosmia (OMIM #614858)." (PMID 34413497, 2021). "Several reports in CHH patients with and without anosmia identified in heterozygosity variants in the WDR11 gene." (PMID 32982993, 2020). "WDR11 is considered to associate with hypogonadotropic hypogonadism with or without anosmia (OMIM#614858)." (PMID 28295047, 2017). "WDR11 binds and colocalizes with the EMX1 transcription factor in the nucleus, and this interaction must be important for its normal function because this capacity is lost by some, although not all, WDR11 mutations in patients with idiopathic hypogonadotropic hypogonadism and Kallmann syndrome." (PMID 28453858, 2017). "We found that the p.I436V mutation, similar to other nearby amino acid substitutions that have been identified in individuals with idiopathic hypogonadotropic hypogonadism with and without anosmia, disrupted interaction of WDR11 with EMX1." (PMID 28453858, 2017).
hypogonadotropic hypogonadism (10 papers, 2017 to 2024). Abnormal ovarian or testicular function due to insufficient hormonal stimulation from the hypothalamic-pituitary axis. "In this study, we report the first case of a truncating variant of WDR11 resulting in a mild form of ciliopathy responsible for central hypogonadism in a male." (PMID 35722485, 2022). "Wdr11-null mice show reduced numbers of GnRH neurons and a reduced expression of the LH beta subunit in males, thus providing experimental support to the biological plausibility for WDR11 mutations to underlie central hypogonadism." (PMID 35722485, 2022). "Heterozygous missense variants in the WD repeat domain 11 (WDR11) gene are associated with hypogonadotropic hypogonadism in humans." (PMID 34413497, 2021). "Heterozygous mutations in the WDR11 gene were described in patients with congenital idiopathic hypogonadotropic hypogonadism (IHH)." (PMID 34946970, 2021). "Only missense variants of WDR11 have been reported to date in patients with central hypogonadism, suggesting that nonsense variants could lead to more complex phenotypes." (PMID 35722485, 2022). "However, the observed human phenotype differs significantly from dominantly inherited variants leading to hypogonadotropic hypogonadism, suggesting that recessive WDR11 variants result in a clinically distinct entity." (PMID 34413497, 2021). "Other rare and novel pathogenic variants in ANOS1, WDR11, FGFR1, RNF216, and CHD7 genes were also found in patients with Congenital Hypogonadotropic Hypogonadism." (PMID 38637882, 2024). "Heterozygous variants were detected in PROK2, WDR11 and CHD7 associated with hypogonadotropic hypogonadism, but these variants are insufficient to contribute to the POI phenotype." (PMID 37988663, 2023). "Monoallelic missense variants in the WD domains located in the central region of the protein have been reported in 7 cases with an autosomal dominant form of central hypogonadism probably resulting from WDR11 haploinsufficiency or a dominant negative effect." (PMID 35722485, 2022).
Intellectual disability (6 papers, 2018 to 2025). "Loss-of-function variants of biallelic WDR11 are associated with intellectual disability and microcephaly." (PMID 40564276, 2025). "A recent study identified biallelic LOF WDR11 variants in association with a complex familial phenotype of microcephaly and intellectual disability." (PMID 35432193, 2022). "We here report biallelic loss-of-function variants in the WDR11 gene in six patients from three independent families with intellectual disability, microcephaly and short stature." (PMID 34413497, 2021). "In conclusion, our data suggest that biallelic loss-of-function variants of human WDR11 are associated with a distinct phenotype that includes pronounced microcephaly, mild short stature and intellectual disability of variable degree." (PMID 34413497, 2021). "In this study, we report for the first time three unrelated families with the core features of intellectual disability, microcephaly, and mild short stature in whom genetic analysis revealed biallelic loss-of-function variants in WDR11." (PMID 34413497, 2021). "Moreover, another recent publication demonstrated that biallelic loss-of-function variants in WDR11 result in a more pronounced phenotype of short stature, pronounced microcephaly and intellectual disability as observed in six patients from three independent families." (PMID 36517585, 2023). "Patients with monoallelic WDR11 and FGFR2 deletions located in 10q26.12q26.2 were predisposed to craniofacial dysmorphisms, growth retardation, intellectual disability and cardiac diseases." (PMID 34256807, 2021).
congenital hypogonadotropic hypogonadism (5 papers, 2018 to 2023). Congenital hypogonadotropic hypogonadism (CHH) is a rare disorder of sexual maturation characterized by gonadotropin (Gn) deficiency with low sex steroid levels associated with low levels of follicle stimulating hormone (FSH) and luteinizing hormone (LH). "A known pathogenic variant in WDR11, which was reported to cause congenital hypogonadotropic hypogonadism (CHH), was identified in individuals with primary hypogonadism." (PMID 35432193, 2022).
Infertility (5 papers, 2018 to 2023). "Notably, Wdr11 was expressed throughout sperm flagella (Fig EV1B) and loss of Wdr11 caused a high frequency (> 50%) of morphologically abnormal sperm, leading to subfertility or infertility." (PMID 29263200, 2018). "The associated phenotype in Wdr11-null mice comprised features of holoprosencephaly such as microcephaly, hypotelorism, microphthalmia/anophthalmia, dysmorphogenesis of the pituitary gland and growth retardation, as well as heart defects, infertility and hypoplasia of reproductive organs." (PMID 34413497, 2021). "Since defective migration of PGCs can result in insufficient numbers of germ cells present in the gonads at birth, leading to infertility or sub-fertility and premature ovarian failure, we investigated if WDR11 participated in PGC development." (PMID 37516749, 2023). "Skeletal defects were found in 32% of Wdr11-knockout mice and eye defects in 15% while infertility was found in 75% of pups." (PMID 34413497, 2021). "Other abnormalities of Wdr11-knockout mice were cardiac defects, dysmorphogenesis of the pituitary gland, hypoplasia of the reproductive organs and infertility." (PMID 34413497, 2021). "WDR11 has been implicated in CHH and KS, human developmental genetic disorders defined by delayed puberty and infertility." (PMID 32982993, 2020).
microcephaly (5 papers, 2018 to 2025). A congenital or acquired developmental disorder in which the circumference of the head is smaller than normal for the person's age and sex. "The phenotype associated with WDR11 loss-of-function variants in humans shows overlap to that found in Wdr11-knockout mice and fish with regard to microcephaly and growth retardation." (PMID 34413497, 2021). "WDR11 is located within the region that is associated with 10q26 microdeletion syndrome which is associated with neurodevelopmental impairment, microcephaly, facial dysmorphism, growth retardation, cardiac defects, coloboma, and urogenital abnormalities." (PMID 34413497, 2021). "In zebrafish, endogenous wdr11 knockdown led to microcephaly and aberrant head cartilage formation, microphthalmia, curved body axis, motility defects, narrow trunk and melanocyte disorganization." (PMID 34413497, 2021). "Moreover, Wdr11-null mice showed features of holoprosencephaly (HPE) that included microcephaly, hypotelorism, microphthalmia or anophthalmia, further craniofacial midline defects or signs of lobar HPE." (PMID 34413497, 2021).
ciliopathies (4 papers, 2018 to 2023). "Child 19 also has a damaging inherited variant in the WDR11 gene that is an integral part of the Hedgehog signaling pathway, with impairments leading to ciliopathies." (PMID 36980938, 2023). "Since Hh signalling requires functional primary cilia and the phenotypes of Wdr11‐null mutants resemble ciliopathy spectrum disorders, we hypothesized that Wdr11 deficiency disrupts normal ciliogenesis." (PMID 29263200, 2018). "Our WDR11 mouse model recapitulated many of the clinical features of human ciliopathies, some of which overlap with the CHH/KS phenotypes." (PMID 29263200, 2018). "WDR11 is a member of the WD repeat containing family and variants of WDR proteins have been associated with various human diseases including neurological disorders, ciliopathies, endocrine disorders and cancer." (PMID 34413497, 2021). "Our study reveals a novel class of ciliopathy caused by WDR11 mutations and suggests that CHH/KS may be a part of the human ciliopathy spectrum." (PMID 29263200, 2018).
glioma (4 papers, 2017 to 2025). A benign or malignant brain and spinal cord tumor that arises from glial cells (astrocytes, oligodendrocytes, ependymal cells). "WDR11 is a member of the WD-repeat gene family and ubiquitously expressed in normal brain and glial tumors." (PMID 29029386, 2017). "Interestingly, there are also hints in the literature that WDR11 acts as a tumour suppressor, since it is disrupted in gliomas." (PMID 39212334, 2025).
gastric cancer (3 papers, 2022 to 2025). A primary or metastatic malignant neoplasm involving the stomach. "WDR11, a gene responsible for encoding a protein in the WD repeat-containing protein family, has been identified as a rare fusion partner with FGFR2 in gastric cancer." (PMID 41357601, 2025).
holoprosencephaly (3 papers, 2018 to 2023). Holoprosencephaly (HPE) is a complex brain malformation resulting from incomplete cleavage of the prosencephalon, occurring between the 18th and 28th day of gestation, and affecting both the forebrain and face, which results in neurological manifestations and facial anomalies of variable severity. "In contrast, knockout of both alleles of Wdr11 in mice results in a more severe phenotype with growth and developmental delay, features of holoprosencephaly, heart defects and reproductive disorders." (PMID 34413497, 2021). "WDR11 may also be an underlying locus for the holoprosencephaly (HPE) spectrum and responsible for many of the phenotypes associated with 10q26 deletion syndrome." (PMID 29263200, 2018). "Wdr11‐null mutants exhibited several characteristics of holoprosencephaly (HPE) associated with Hh signal deficiency." (PMID 29263200, 2018).
hypogonadism (3 papers, 2022 to 2023). A disorder characterized by decreased function of the gonads. "Interestingly, Wdr11-null mice have decreased LHβ-subunit but normal FSHβ-subunit expression, suggesting the existence of a dissociated hypogonadism, which could explain the observation in our patient." (PMID 35722485, 2022). "However, current data suggest that defects within the gonads (a ‘primary’ hypogonadism) may exist in individuals with WDR11 mutations, especially those who failed to respond to gonadotropin therapy." (PMID 37516749, 2023).
hypospadias (3 papers, 2016 to 2019). Hypospadias is the displacement of the urethral meatus on the ventrum of the penis. "Patient 7 presented five variants in five genes: EVC, MAML3, NOTCH2, PPARGC1B and WDR11; four of them associated with hypospadias or male gonadal development and one, MAML3, with female gonadal development." (PMID 31555317, 2019). "We conclude that variants in CHH genes, in particular PROKR2, PROK2, WDR11 and FGFR1 with CHD7, may contribute to under-virilisation phenotypes including hypospadias in Indonesian boys." (PMID 28209183, 2017). "We postulate that variants in CHH genes, in particular PROKR2, PROK2, WDR11 and FGFR1 with CHD7, may contribute to under-virilisation phenotypes including hypospadias in Indonesia." (PMID 28209183, 2017).
glioblastoma (2 papers, 2017 to 2023). The most malignant astrocytic tumor (WHO grade IV). "WDR11 (WD repeat domain 11, MIM 606417) is a gene that has been previously found to be involved in tumorigenesis of human glioblastoma cells." (PMID 36517585, 2023).
Obesity (2 papers, 2018 to 2021). Accumulation of substantial excess body fat. "Another maternally inherited WDR11 missense variant with reduced penetrance has been associated with pituitary dysgenesis, growth hormone deficiency and obesity in two brothers." (PMID 34413497, 2021). "We further show that loss of WDR11 leads to obesity in both mice and men, suggesting that Hh signalling via WDR11 is one of the key links between reproduction and metabolism." (PMID 29263200, 2018).
anxiety disorder (1 paper, 2018). A category of psychiatric disorders which are characterized by anxious feelings or fear often accompanied by physical symptoms associated with anxiety. "Here, we additionally report a novel WDR11 mutation associated with pituitary dysgenesis, anxiety disorder and childhood obesity." (PMID 29263200, 2018).
developmental delays (1 paper, 2021). "Therefore, WDR11 and FGFR2 deletions might be responsible for the clinical characteristics of the present case, such as global developmental delays, cardiac defects and facial abnormalities." (PMID 34256807, 2021).
Hydrocephalus (1 paper, 2018). Hydrocephalus is an active distension of the ventricular system of the brain resulting from inadequate passage of CSF from its point of production within the cerebral ventricles to its point of absorption into the systemic circulation. "The abnormal choroid plexus present in Wdr11−/− brain, which led to hydrocephalus, contained much fewer epithelial cilia compared to the WT, although the overall axonemal structure appeared normal." (PMID 29263200, 2018).
pituitary disease (1 paper, 2017). "Although we report on heterozygous mutations in both PROKR2 and WDR11 in the same individual, each of these genes has previously been implicated with another gene mutation as the basis for a digenic pituitary disease." (PMID 28453858, 2017).
pituitary hormone deficiency (1 paper, 2021). "Furthermore, a patient with combined pituitary hormone deficiency was found to have a maternally inherited splice-site variant in WDR11 (NC_000010.11:g.120860107A>G; NM_018117.12:c.353-2A>G), that presumably leads to a 58 amino acid deletion/1 amino acid insertion." (PMID 34413497, 2021).
primary hypogonadism (1 paper, 2022). "A variant in WDR11, previously reported to cause CHH, was identified in individuals with primary hypogonadism suggesting that heterozygous variants in this gene may not always cause CHH." (PMID 35432193, 2022).